H19 (H19 imprinted maternally expressed transcript)
Diseases named in the same sentence as H19 in open-access papers (continued):
Sharing a sentence is not in itself a finding about the gene and the disease.
tumor (continued). "In this aspect H19/miR-675 may impose its tumor suppressive role through acting as a pro-differentiating factor or may function as an oncogene by promoting stemness/de-differentiating process." (PMID 26623562, 2016). "The oncogenic properties of H19 were strongly associated with antagonism of the tumor suppressor miRNA let-7 and forced EMT mediated by the non-histone chromosomal transcriptional regulator HMGA2." (PMID 27686732, 2016). "Interestingly, H19 has been reported to be either upregulated or downregulated in HCC compared with non tumour liver, suggesting a high variability across different cohorts of patients." (PMID 26887054, 2016). "LincRNA H19 is involved in tumor development, progression and metastasis." (PMID 27193186, 2016). "Therefore, we conducted a meta-analysis to evaluate the value of H19 with tumor metastasis and progression in a larger sample size of patients." (PMID 27672656, 2016). "Besides, several researches reported that H19 plays an important role in tumor metastasis by promoting epithelial to mesenchymal transition." (PMID 26989025, 2016). "Previous studies have shown that H19 bears both oncogenic and tumor-suppressive properties." (PMID 26983719, 2016). "The expression of H19 in an individual biopsy may be considered a predictive tumor marker for selecting those patients who would benefit from this form of treatment." (PMID 27193186, 2016). "H19 was the first lncRNA reported as a tumor suppressor in mammalian cells in 1993." (PMID 26230711, 2015). "As already described for other lncRNAs, H19 can work as a microRNA sponge, miRNAs precursor, or epigenetic modulator, and has been found overexpressed in several tumors, and able to promote tumor growth and progression." (PMID 26272696, 2015). "In contrast, miR-675, the miRNA derived from H19, exhibits antagonistic behavior and functions as a tumor suppressor by repressing the IGF1R (Insulin like Growth Factor 1 Receptor) expression, thus the levels of these two transcripts help in maintaining cellular homeostasis." (PMID 26082843, 2015). "In conclusion, plasma H19 could serve as a potential biomarker for diagnosis of GC, in particular for early tumor screening." (PMID 26096073, 2015). "But regardless of its involvement in proliferation that may indirectly promote malignancy, recent studies by us and others show that H19 promotes tumor metastasis by direct involvement in malignant processes." (PMID 26536864, 2015). "Long non-coding RNA (lncRNA) H19 is involved in tumor development, progression, and metastasis." (PMID 25944697, 2015). "Moreover, increased expression of H19 positively regulated in vitro colony formation as well as in vivo tumor growth." (PMID 26068968, 2015). "Taken together, we clearly demonstrated that plasma levels of H19 may potentially be useful for cancer screening and monitoring tumor dynamics in GC patients postoperatively." (PMID 26096073, 2015). "Moreover, we clearly demonstrated that plasma H19 levels are useful to detect GC and monitor tumor dynamics for tumor resection." (PMID 26096073, 2015). "In support of our suggestion, H19 expression leads to growth retardation, abrogation of clonogenicity and impaired in vivo tumorigenesis, but these findings were manifested in embryonic tumor cell lines." (PMID 26536864, 2015). "Patient selection is achieved using labeled H19 riboprobe in-situ hybridization of tumor samples." (PMID 25884481, 2015). "In the metastatic tumor stage, which bears a striking similarity to the embryonic stage, H19 involvement appears to be essential: adherent and cohesive cells lose their anchorage, migrate under stressful conditions to remote sites and replicate with neovascular support." (PMID 25884481, 2015). "Curcumin treatment of various tumor cell types resulted in H19 suppression." (PMID 26536864, 2015).
tumor (continued). "H19 provided the high diagnostic power for detection of GC (AUC = 0.838; sensitivity, 82.9%; and specificity, 72.9%), suggesting that plasma H19 could serve as a promising tumor marker for GC detection." (PMID 26096073, 2015). "Strikingly, H19 may induce and activate tumor-specific pyruvate kinase M2 (PKM2) which is essential for the Warburg effect in its dimer and for gene expression in its teramer during tumorigenesis." (PMID 26376677, 2015). "Numerous studies including ours indicate that H19 may play a key role in tumorigenesis and could contribute to tumor progression and aggressiveness." (PMID 25972893, 2015). "Furthermore, the cell proliferation marker Ki-67 was used for evaluating in vivo tumor growth and enhanced Ki-67 expression was observed in H19-overexpressing tumor tissue, suggesting a potential oncogenic effect of H19." (PMID 26068968, 2015). "Next, we investigated whether plasma H19 concentrations could reflect tumor dynamics in GC by two different analyses." (PMID 26096073, 2015). "Importantly, xenograft tumor was greater in H19 overexpressed group than that in control (1.75±0.12 gram vs 0.57±0.19gram, P < 0.01)." (PMID 26376677, 2015). "Furthermore, H19 expression has been correlated with tumor invasion in the reproductive organs and neoplastic cell invasion of the myometrium." (PMID 25101115, 2014). "In addition, H19 can also regulate gene expression post-transcriptionally by serving as a precursor for the miRNA-675, which directly targets the tumor suppressor Retinoblastoma (Rb)." (PMID 24346158, 2014). "Kim and Lee (1997) firstly found that the expression of H19 usually shift from monoallelic to biallelic in HCC and it might play a causal role in the epigenetic mechanism involved in tumor development and/or process." (PMID 25387074, 2014). "Furthermore, we focus on major transcriptional modulators of the H19 gene and discuss them in the context of the tumor-promoting activity of the H19 RNA." (PMID 23429271, 2013). "Moreover, the H19 gene is expressed within both epithelial and stromal components of human invasive adenocarcinomas, where high expression matches tumor invasion." (PMID 23429271, 2013). "As one of the first imprinted genes discovered, H19 was initially identified as a tumor suppressor because embryo-derived tumor cells overexpressing H19 exhibited growth retardation, morphological changes and abrogated clonogenicity in soft agar, as well as suppressed tumorigenicity in nude mice." (PMID 23711233, 2013). "Results from previous studies have initiated a debate as to whether noncoding RNA H19 acts as a tumor suppressor or as a tumor promotor in trophoblast tissue." (PMID 23711233, 2013). "Patients are eligible for the treatment with BC-819 only if their tumor is positive for H19 RNA." (PMID 23429271, 2013). "The progeny of the H19-expressing cells will increase in number at a higher rate than the neighboring cells and, hence, gradually increase their relative contribution to the tumor volume." (PMID 23429271, 2013). "Thus, BC-819 has the potential to treat several types of cancer, provided the involved tumor cells express the H19 gene, while sparing healthy cells from the DTA-mediated toxicity." (PMID 23429271, 2013). "In summary, the 91H RNA could be assumed to be oncogenic by favouring Igf2 transcription while H19, which counteracts this effect, would act as a tumour suppressor." (PMID 22662250, 2012). "However, several studies have also shown that the H19 RNA can accumulate in cancer cells and tumours and it has been considered as an oncofetal RNA by some authors." (PMID 22662250, 2012). "It was recently confirmed that, in the mouse, H19 acts as a tumour suppressor." (PMID 22662250, 2012).
tumor (continued). "The discrepancy as to whether H19 has oncogenic or tumor suppressive potential may be due in part to the bifunctional nature of the lncRNA or may be context dependent." (PMID 21489289, 2011). "Tumor cells can express high levels of H19 and IGF2, or only one of those genes." (PMID 21162716, 2010). "However the total combined expression of both IGF2-P4 and H19 transcripts, were detected at high expression levels in 100% (29/29) of the tumor samples." (PMID 21162716, 2010). "Moreover, the total combined expression of both IGF2-P4 and H19 transcripts was detected at high expression levels in 100% (29/29) of the tumor samples." (PMID 21162716, 2010). "Thus, the H19-DTA-P4-DTA vector exhibits augmented-than-additive in vivo tumor growth inhibition activity, compared to the combined activity of both single-promoter constructs (H19-DTA and P4-DTA)." (PMID 21162716, 2010). "However, three injections of the double promoter plasmid H19-DTA-P4-DTA at two-day intervals inhibited tumor development by 70% (P < 0.001) compared to H19-Luc-P4-Luc treatment." (PMID 21162716, 2010). "By that the targeted destruction of cancer cells expressing IGF2 or H19, companied by enhanced bystander effect, may lead to arrest of tumor growth and prevent following metastases process." (PMID 21162716, 2010). "Furthermore, very low expression levels of H19 mRNAs and substantial expression levels of IGF2 mRNAs in HB tumours with UPD or LOI, and substantial expression levels of both IGF2 and H19 mRNA in HB tumours with ROI were found." (PMID 19034281, 2008). "We analysed the methylation status of the H19 differentially methylated region (DMR), loss of heterozygosity (LOH) and allelic expression of IGF2 in 54 HB tumours, and found that 12 tumours (22%) with LOH, 9 (17%) with loss of imprinting (LOI) and 33 (61%) with retention of imprinting (ROI)." (PMID 19034281, 2008). "23, 24, 26 and 27) of 13 HB tumours with normally methylated H19 DMR (ROI) remains unresolved." (PMID 19034281, 2008). "Putative tumor suppressor genes are upregulated by H19 knockdown in hypoxic stress." (PMID 17786216, 2007). "As can be seen, AFP is also expressed in the intravascular invasion of HCC, possibly teaching that H19 could serve as a tumor marker." (PMID 17786216, 2007). "H19 RNA harbors pro-tumorigenic properties, thus the H19 gene behaves as an oncogene and may serve as a potential new target for anti-tumor therapy." (PMID 17786216, 2007). "Previous reports have shown the LOI of H19 in many tumor types." (PMID 17786216, 2007). "In the current study, we highlight a critical role of H19 RNA in tumor development." (PMID 17786216, 2007). "For another three tumours that were not informative for polymorphisms (#6, #8, and #10), methylation of H19-pro-DMR and DMR-LIT1 was maintained, so they were considered to show ROH." (PMID 16909133, 2006). "Decreased IGF2 and H19 mRNA levels were found in five (21%) and three (13%) tumours, respectively." (PMID 10944603, 2000). "All informative tumours demonstrated monoallelic expression of H19." (PMID 10732739, 2000). "Other studies have indicated that H19 may have tumor suppressor functions in HCC." (PMID 40699668, 2025). "Interestingly, H19-induced tumor suppression is superior to cabergoline treatment." (PMID 40362297, 2025). "Thus, overexpression of the lncRNA H19 in the tumor microenvironment may impair T cell proliferation through diminishing IL-2 levels." (PMID 40429961, 2025). "Interestingly, in a mouse colorectal model, it has been shown that exosomal H19 is not produced by tumor cells but, instead, by cancer-associated fibroblasts (CAFs)." (PMID 40429961, 2025). "Additionally, the level of circulatory H19 was found to decrease following tumor removal." (PMID 38166752, 2024). "Additionally, the abnormal expression of lncRNAs such as H19 and MALAT1 in BTC is strongly associated with tumor progression, suggesting that targeting these lncRNAs could offer new therapeutic strategies." (PMID 39857631, 2024).
tumor (continued). "Our working hypothesis is that patients developing metastasis exhibit a tumor micro-environment characterized by altered estrogen and hypoxia signaling that activates the H19/cell adhesion molecules circuitry, governing the metastatic program toward a collective cancer cell migration." (PMID 39457633, 2024). "In addition, another study reported that the expression level of miR-675 reflected tumor dynamics more accurately than H19 and may represent a new biomarker for the diagnosis, prognosis, and monitoring of therapeutic responses in HCC." (PMID 36960964, 2023). "They observed that H19 repression inK562 cell line could significantly inhibit tumor progression." (PMID 36680478, 2023). "Similarly, H19 is one of the first long noncoding RNA identified; it is expressed in a menstrual cycle-dependent fashion, confined to the stroma, and acts as a decoy for several tumor-suppressor miRNA." (PMID 36387918, 2022). "When combined with paclitaxel, silencing H19 could enhance tumor inhibition in vivo." (PMID 36246634, 2022). "However, controversy remains regarding the potentially tumour suppressive or oncogenic role of H19." (PMID 35166018, 2022). "In summary, the present study further investigated the roles of ER stress modulation and lncRNA H19 expression in resveratrol treatment, while our results indicated that regulation of ER stress and lncRNA expression may enhance the anti‐tumour function of resveratrol." (PMID 35166018, 2022). "Additionally, exosomal H19 targets gefitinib-sensitive tumor cells to spread gefitinib resistance." (PMID 36362424, 2022). "H19 may promote the proliferation and migration of tumor cells." (PMID 36188624, 2022). "Moreover, tumor volume and tumor weight were all inhibited by H19-silenced TAMs-exo administration." (PMID 35607322, 2022). "This suggests that H19 may be involved in tumor drug resistance mechanisms." (PMID 34922547, 2021). "However, H19 has also been found to have cancer suppressing activity, which can inhibit the malignant proliferation, invasion, and metastasis of tumors, and the formation of tumor neovascularization." (PMID 33403385, 2021). "However, H19 plays different roles in the different stages of tumor initiation and progression, so it is still controversial as to whether H19 is truly an oncogene or a tumor suppressor gene." (PMID 33931980, 2021). "Our results have demonstrated that H19/miR-675 and LNC000093 from leukemic cells are transported through extracellular vesicle exosomes and exert effects on BMSCs to alter the expression of VEGF, which is a representative promoter of tumor angiogenesis and is associated drug resistance." (PMID 34414175, 2021). "The aberrant expression of lncRNAs, exemplified by lncRNA H19 and lncRNA 91H, an antisense gene of H19, has been implicated in the tumorigenesis and metastasis of different types of cancer, including CRC, where it is associated with a poor prognosis and a high risk of tumor metastasis." (PMID 34070617, 2021). "Additionally, mean values of tumor weight in H19 knockdown mice was remarkably reduced." (PMID 34796112, 2021). "Moreover, serum levels of H19 showed a significant positive correlation with tumor grade." (PMID 34322395, 2021). "However, there is always a debate about whether H19 works as an oncogenic factor or a tumor suppressor." (PMID 34885213, 2021). "There is controversy about whether H19 acts as a tumor suppressor gene or oncogenic factor." (PMID 34977037, 2021). "Moreover, knockdown of H19 inhibited tumor metastasis in vivo." (PMID 34069428, 2021). "Silencing H19 could be an effective method to suppress tumor growth." (PMID 34421359, 2021). "Additionally, H19 could bind eIF4A3 to promote cell growth and influence tumor differentiation and TNM stage in CRC patients." (PMID 34421359, 2021).
tumor (continued). "Moreover, knocking down H19 could suppress the migration and invasion of tumor cells and delay the progression of transplanted tumor and lung metastasis in nude mice." (PMID 33520725, 2020). "Results of our study revealed that H19 KO via CRISPR/Cas9 system could inhibit tumor growth." (PMID 32485786, 2020). "However, it is unclear whether the induction of H19 or IGF2 by Phb1 knockout leads to tumor development." (PMID 32429417, 2020). "H19 could simultaneously function as a tumor suppressor and an oncogene." (PMID 33193379, 2020). "LncRNA H19 could also be acted as a tumor suppressor to inhibit the pituitary tumor growth." (PMID 32192168, 2020). "Furthermore, the expression of H19 did decrease with tumor volume." (PMID 32498309, 2020). "It seems that H19 may not be the best target for the function of NSUN2 in tumor which NSUN2 deficiency significantly inhibited cancer cell proliferation and migration." (PMID 32978516, 2020). "Furthermore, a role for H19 acting either as a tumour suppressor or an oncogene has been suggested." (PMID 32301281, 2020). "Based on our previous results showing that H19 correlates with the tumor differentiation of human PC, we speculated that H19 may play essential roles in regulating the stemness, epithelial-mesenchymal transition (EMT), invasion and chemosensitivity of PC cells." (PMID 32626524, 2020). "Therefore, plasma H19 may be a promising tumor marker for GC; however, many questions remain to be resolved before these findings can be translated into clinically useful, non-invasive screening strategies for GC patients." (PMID 32754285, 2020). "The critical role of altered H19 expression, TGF-β signaling, and ECM deposition in the pathogenesis of UFs is further underscored by findings from genome-wide association studies revealing SNPs in H19, TGFBR2, and GRAF1 that affect both the risk and tumor size of UFs." (PMID 31089260, 2019). "Similarly, H19 can play opposite roles on tumor metastasis at different stages." (PMID 30984483, 2019). "In addition, in vivo experiments we have also confirmed that H19 promoted tumor growth and may develop resistance to bortezomib partly." (PMID 30728351, 2019). "A previous study implied that H19 may function as a tumor suppressor." (PMID 31787851, 2019). "This may be the mechanisms why H19 is the tumor suppressor in PTC and promoter in ATCs." (PMID 31299871, 2019). "The H19 gene might be an effective target for tumor molecular therapy." (PMID 31299871, 2019). "Moreover, in vivo experiments, we showed that overexpression of H19 could significantly promote tumor growth and counteract the antitumor effect of miR-29b." (PMID 30728351, 2019). "Therefore, H19 downregulation inhibits tumor metastasis in vivo." (PMID 31299871, 2019). "Although our experimental design has its limitations due to the difficulty in determining the dosages and concentration of CAB to be used, which could affect the outcome of our results, our data show that CAB treatment was less potent than H19 overexpression in suppressing tumour growth in vivo." (PMID 30397197, 2018). "Thus, it remains controversial as to whether H19 functions as a tumor promoter or a tumor suppressor." (PMID 29703210, 2018). "Whether H19 acts as an oncogene or as a tumor suppressor gene is controversial." (PMID 29495592, 2018). "In addition, H19 expression was increased sharply in many cancer cell lines of liver, bladder, lung, ovarian and breast under the condition of hypoxic stress, which occurs commonly in tumor development." (PMID 28230721, 2017). "It is known that H19 and miR-675 may play a dual role in tumor progression and development." (PMID 28212565, 2017). "In addition, these proteins are actively involved in a wide variety of physiological and pathological processes such as RNA metabolism, gene transcription, epigenetic modification, skeletal muscle differentiation and tumor development, suggesting a diversified function of H19." (PMID 28230721, 2017).